ALKBH3 (alkB homolog 3, alpha-ketoglutarate dependent dioxygenase)
Diseases named in the same sentence as ALKBH3 in open-access papers (continued):
Sharing a sentence is not in itself a finding about the gene and the disease.
tumor (43 papers, 2011 to 2026). "Due to the possibility that MAQ probes can measure ALKBH3 activity to measure patient response to treatment, many studies have linked ALKBH3 to tumor growth." (PMID 37007161, 2023). "Secondly, by using DNA samples available from a subset of the same tumor samples as analysed with respect to ALKBH3 expression, we were able to assess the association between mRNA expression levels and promoter methylation status." (PMID 28679371, 2017). "We also assessed association with senescence and in vivo ALKBH3 treatment on orthotopic tumour cell inoculation, and analysed it clinicopathologically." (PMID 21285982, 2011). "ALKBH3 depletion also caused dramatic increases in the size and weight of subcutaneous tumours." (PMID 39175405, 2024). "In addition, the expression of 5′-tRF-GlyGCC level was significantly and positively associated with the expression of ALKBH3 in tumor-bearing mice." (PMID 33563322, 2021). "In ocular melanoma, lactate-induced H3K18 lactylation activates ALKBH3 transcription, promoting tumor cell migration and invasion." (PMID 40859309, 2025). "Silencing ALKBH3 results in the halting of tumor cell cycle progression by influencing NOX-2 to increase ROS activity." (PMID 40809690, 2025). "Among them, ALKBH3 primarily influences various signaling pathways to regulate the cell cycle and invasiveness of tumor cells." (PMID 39687616, 2024). "Pseudouridylation of alpha ketoglutarate-dependent dioxygenase (ALKBH3), a tumor suppressor gene, can enhance the translation of ALKBH3 and reduce tumor growth." (PMID 39852793, 2024). "AGTRAP, DIVERSIN, cytoplasmic NEDD8 (NEDD8c) and RRM1 were significantly overexpressed in tumour tissues compared to the healthy brain, while the opposite was observed for ALKBH3." (PMID 38672281, 2024). "While some studies found that ALKBH3 was overexpressed in tumour tissues and exhibited tumour-promoting functions, others showed that ALKBH3 was epigenetically inactivated in certain malignancies." (PMID 38672281, 2024). "Macroscopically subcutaneous tumours of PUS7‐depleted MKN45 cells were robustly diminished by exogenous expression of ALKBH3 or PUS7." (PMID 39175405, 2024). "It is previously reported that ALKBH3 regulates angiogenesis and tumor invasion through NOX2-ROS and Tweak/Fn14/VEGF." (PMID 37612524, 2023). "In the hormone-dependent prostate cancer cell line DU145, silencing ALKBH3 significantly induced apoptosis, inhibiting its tumorigenicity, tumor-forming size, and anchor growth in vivo." (PMID 37007161, 2023). "The upregulation degree of ALKBH3 was correlated with tumor proliferation ability, prognosis, and survival time." (PMID 37007161, 2023). "The highest mRNA expression levels of ALKBH2 and ALKBH3 were found in tumor N3 and were significantly correlated." (PMID 34150745, 2021). "m6A-modified mammalian tRNA has been identified as a novel ALKBH3 substrate, highlighting a novel role for ALKBH3 in tumor progression via RNA demethylation and subsequent promotion of protein synthesis." (PMID 34692544, 2021). "The results proved that ALKBH3 expression was lower in tumor compared to normal tissues, TRMT61A expression differences were not meaningful and the rest were expressed higher in OC." (PMID 34777359, 2021). "Given the observed impact on disease progression, this second method is more likely to hold relevant at least as a proxy for identifying tumours affected by ALKBH3 promoter methylation." (PMID 28679371, 2017). "We previously reported the high expression of ALKBH3 in clinical tumor specimens and its involvement in tumor progression." (PMID 28205560, 2017). "RNA samples available from normal breast tissue and tumor samples were used to assess ALKBH3 mRNA expression." (PMID 28679371, 2017). "The second method refers to making use of clinical parameters involving tumour phenotype or disease survival to then declare a “clinically relevant” threshold for defining ALKBH3 promoter methylated tumours." (PMID 28679371, 2017).
tumor (continued). "The numbers of tumours formed in the peritoneum in our nude mouse model were significantly decreased in mice receiving ALKBH3 siRNA compared with mice receiving control siRNA." (PMID 21285982, 2011). "This study does not include prospective tumour DNA sequencing and therefore investigation of the impact of germline variants in novel genes such as ALKBH3 has not been possible so far." (PMID 39516637, 2024). "Histone lactylation increases the expression of ALKBH3 thereby accelerating tumor." (PMID 38779665, 2024). "Furthermore, in human urothelial carcinoma cells, ALKBH3 enhances tumor survival, invasiveness, and angiogenesis by modulating the production of reactive oxygen species and the expression of several critical factors like VEGF." (PMID 39687616, 2024). "Therefore, it is possible to explore inhibitors targeting ALKBH3, block the CSF-1/CSF-1R signaling pathway, and develop epigenetic therapies targeting m1A modification to control tumor progression." (PMID 39687616, 2024). "Additionally, PUS7 enhances the translation efficiency of ALKBH3 mRNA by modifying the U696 site with pseudouridine, thereby attenuating tumour growth." (PMID 39175405, 2024). "Furthermore, PUS7 attenuates tumor growth by modifying the U696 site with pseudouridine, thereby increasing the translation efficiency of the ALKBH3 mRNA." (PMID 39737343, 2024). "Knockdown of ALKBH3 inhibits tumor anchorage growth and migration." (PMID 37007161, 2023). "m1A demethylation induced by ALKBH3 can promote protein synthesis in tumour cells." (PMID 36147503, 2022). "ALKBH1 and ALKBH3 were both lowly expressed in tumor and normal samples." (PMID 34777359, 2021). "ALKBH3, a demethylase for m1A, promotes mRNA stability of CSF1, which regulates the density of tumor-associated macrophages and CD3+ T lymphocytes via its demethylation activity and leads to poor prognosis in breast cancer." (PMID 33741974, 2021). "Interestingly, in type T2 tumours, the level of ALKBH3 was similar or slightly higher than in adjacent tissue, whereas in type T4 tumours ALKBH3 level was strongly elevated in comparison to unaffected surrounding tissue." (PMID 31519943, 2019). "In this study, two different methods are applied for this purpose, i.e. 1) making use of normal tissue samples as reference to then define “abnormally” high levels of ALKBH3 promoter methylation in tumours and 2) by identifying clinically relevant levels of ALKBH3 promoter methylation." (PMID 28679371, 2017). "Thus, our data highlight a novel role for ALKBH3 in tumor progression via RNA demethylation and subsequent protein synthesis promotion." (PMID 28205560, 2017). "Out of the 265 primary tumors analysed with respect to ALKBH3 promoter methylation, a subset of 30 tumor samples were matched with adjacent normal breast tissue samples from the same patients – thereby enabling assessment of differential methylation in paired samples." (PMID 28679371, 2017). "Consequently, it seems likely that ALKBH3 mediates its tumor suppressive function via its role in DNA alkylation repair." (PMID 28679371, 2017). "According to our results, ALKBH3 represents a candidate tumor suppressor gene." (PMID 28679371, 2017). "In vivo, peritoneal tumour growth and dissemination was inhibited in nude mice, previously inoculated with the A549 cell line, by intraperitoneal injection of ALKBH3 siRNA + atelocollagen, as demonstrated by the reduction in both number and diameter of tumours developing in the peritoneum." (PMID 21285982, 2011). "Moreover, we found high levels of 5′-tRF-GlyGCC in CRC might be due to the upregulation of tRNA demethylases ALKBH3 by analyzing data from cellular, tumor bearing mice." (PMID 33563322, 2021). "Our immunohistochemical analysis further suggests that the ALKBH3 expression profile of tumours may be a predictive factor for tumour recurrence of adenocarcinoma, in particular, and may also join EGFR mutational analysis as a marker for sensitivity to chemoradiation." (PMID 21285982, 2011).
tumor (continued). "ALKBH3-dependent m1A demethylation promotes SP100A mRNA stability and translational efficiency to yield SP100A protein levels and subsequent tumor suppressive functions down the line of this factor." (PMID 41188771, 2025). "Mechanistically, ALKBH3 removes m1A modification from SP100A mRNA, a tumor suppressor, reducing its stability and translational efficiency." (PMID 40859309, 2025). "Among the regulatory genes, ALKBH1 and ALKBH3, which are methylation erasers, were upregulated and TRMT10C, TRMT6, TRMT61B, YTHDF2, and YTHDF3 were downregulated in tumor samples in comparison to normal tissues." (PMID 37679761, 2023). "There is furthermore evidence from an orthotopic model of urothelial carcinoma that ALKBH3 in cooperation with an autocrine TWEAK-Fn14 loop maintains expression of Fn14 and VEGF in tumor vessels to promote angiogenesis and tumor progression." (PMID 36339601, 2022). "ALKBH3 knockdown inhibited human HCC cell proliferation in vitro and xenograft tumor formation in vivo, presumably through p21/p27-mediated cell cycle arrest at the G1 phase." (PMID 34692544, 2021). "Further, we demonstrated that ALKBH3 and FTO levels are correlated with primary tumour size (T in TNM classification): protein expression was higher in larger T4 tumours, as compared to smaller T2 tumours." (PMID 31519943, 2019). "We detected significantly higher levels of ALKBH3 and FTO in larger primary tumours (type T4 in TNM classification), as compared to smaller ones (type T2 in TNM classification)." (PMID 31519943, 2019). "In tumor immunity, metabolic disorders, and aging-related diseases, m1A modification enzymes (such as TRMT6/TRMT61A, ALKBH3) may serve as potential intervention targets." (PMID 40809690, 2025). "Overall, our results demonstrate that ALKBH3-dependent m1A demethylation is essential for the formation of PML nuclear bodies, thereby providing a novel therapeutic strategy in which the ‘targeted m1A reprogramming strategy’ is efficient for tumor therapy." (PMID 38118002, 2024). "We found direct correlation of ALKBH3 and FTO expression with primary HNSCC tumor size." (PMID 31519943, 2019). "Firstly, these data provide additional support for differential methylation over the ALKBH3 promoter region between normal breast tissue and tumours (data not shown)." (PMID 28679371, 2017). "Declaring tumours as either ALKBH3 promoter methylated or unmethylated is therefore not a straightforward task." (PMID 28679371, 2017). "Making use of normal breast samples as a reference, does not necessarily provide a means to identify tumours showing ALKBH3 inactivation events." (PMID 28679371, 2017). "Furthermore, the progressive suppression of ASCC2, ALKBH3, E2F1, and G6PD led to a marked decrease in their immunohistochemical staining scores, indicating reduced protein expression and altered cellular localization within the tumor microenvironment." (PMID 41484982, 2026). "Histone lactylation can upregulate AlkB homolog 3 (ALKBH3), which in turn suppresses m1A modification of speckled protein 100A (SP100A), weakening the formation of tumor-suppressive promyelocytic leukemia (PML) protein condensates and facilitating the malignant transformation of tumor cells." (PMID 40584966, 2025). "Thus, the content of ALKBH3 and FTO increases along with the tumour size." (PMID 31519943, 2019). "In conclusion, rhein inhibited AlkB repair enzymes (AlkB, ALKBH2, and ALKBH3) in vitro and reduced cell resistance to MMS, and it was speculated that ALKBH2 and ALKBH3 enzymes may be effective pharmacological targets for overcoming tumor resistance to methylated anticancer drugs." (PMID 34457021, 2021).
ALKBH3 also shares sentences with these, for which no sentence is quoted: hepatocellular carcinoma (5 papers); colon cancer (2); Obesity (2); adenocarcinoma (1); anemia (1); cardiovascular diseases (1); colon adenocarcinoma (1); digestive system neoplasm (1); Duchenne muscular dystrophy (1); esophageal carcinoma (1); fibrosis (1); glioblastoma (1); head and neck squamous cell carcinoma (1); inflammatory bowel disease (1); leukemia (1); metastatic cancers (1); nervous system diseases (1); spinal muscular atrophy (1); squamous cell carcinoma (1); stomach adenocarcinoma (1); ulcerative colitis (1).